MIR519A1 (microRNA 519a-1)
Synonyms: hsa-mir-519a-1; MIRN519A-1; MIRN519A1; mir-519a-1
Gene: MicroRNA gene on chromosome 19 (53,752,397 to 53,752,481, forward strand). Ensembl gene ENSG00000207992.
Gene Ontology:
Biological process: miRNA-mediated post-transcriptional gene silencing